IGF1R (insulin like growth factor 1 receptor)
Diseases named in the same sentence as IGF1R in open-access papers (continued):
Sharing a sentence is not in itself a finding about the gene and the disease.
glioma (continued). "In 2010, PPP was shown to lower IGF-1R and AKT phosphorylation and impede the development of human glioma cell lines." (PMID 36555406, 2022). "PQ-401 is an IGF-1R inhibitor that induces apoptosis and inhibits in vitro viability, proliferation, and mobility of U87MG glioma cells and in vivo glioma tumor growth in a mouse xenograft model." (PMID 36499305, 2022). "CPD protein is known to process pro-IGF1R into its mature form and we recently showed that CPD is also involved in maturation of MET receptor protein specifically in glioma cells." (PMID 36443674, 2022). "It is known that IGF1 has direct effects on stimulating glycolytic flux favoring tumor cell energy production, acting through IGF1R to increase the GLUT1 expression, the main glucose transporter in glial tumors." (PMID 35574033, 2022). "miRNA-323-5p regulated insulin-like growth factor 1 receptor (IGF-1 R) and suppressed human glioma cellular growth and enhanced apoptosis." (PMID 35287547, 2022). "Further studies demonstrated that IGF1R was a direct target of miR-383, which regulated the IGF1R/AKT signaling pathway and MMP2 expression, thereby influencing glioma cell invasion." (PMID 34976192, 2022). "Hence, intracellular IGF1R localization may help in stratifying pediatric glioma patients." (PMID 33918477, 2021). "Taken together, these observations demonstrate that deletion of IGF1R severely compromises the progression, and likely also the initiation, of OPC‐originated glioma." (PMID 33173731, 2020). "Finally, we tested whether IGF1R could function as the TIC markers for human glioma cells." (PMID 33173731, 2020). "As an example, in glioma, the downregulation of miR-383 stimulates AKT signaling and controls the expression of Matrix Metalloproteinase II (MMP2), through the regulation of IGF-1R, thereby controlling tumor cells invasiveness." (PMID 30469501, 2018). "Since TMZ-sensitive glioma cells produce IGFBP6, we evaluated the effects of conditioned medium from TMZ-sensitive U251 cells on IGF2-dependent phosphorylation of IGF-1R and AKT expressed by TMZ-resistant UTMZ glioma cells." (PMID 30231881, 2018). "We determined that in human glioma tissue, glioma cell lines, and patient-derived xenograft cell lines, treatment with TMZ enhances the expression of IGF1 receptor (IGF-1R) and IGF2 and decreases the expression of IGFBP6, which sequesters IGF2." (PMID 30231881, 2018). "We have characterized a population of chemoresistant glioma cells in which AKT is activated through the binding of IGF2 to IGF-1R and indirectly repressed by IGFB6 secreted from chemosensitive glioma cells." (PMID 30231881, 2018). "Our results do not however address the origins of heterogeneity, and leave open the issue of how amplified IGF2+/IGF-1R+ and IGFBP6+ subpopulations arise during the establishment of a glioma." (PMID 30231881, 2018). "The analysis of glioma stem cells further demonstrated that fractionated radiation promotes both an increase in IGF1 secretion and a gradual upregulation of the IGF1R, which confer radioprotective effects on resistant cells." (PMID 28880250, 2017). "Our result revealed that the protein levels of IGF1R, IRS1, mTOR, and Bcl‐2 were increased in TMZ‐resistant glioma cells (U87‐TR and SF295‐TR) compared with TMZ‐sensitive glioma cells (U87 and SF295)." (PMID 28064447, 2017). "Therefore, the IGF/IGF-1R signaling pathway may be a potential target for the treatment of glioma." (PMID 26035416, 2015). "In the present study, the antitumor activity of a small-molecule inhibitor of IGF-1R, GSK1904529A, in glioma was assessed." (PMID 26035416, 2015). "Thus, miR-7 could directly regulate the IGF-1R/Akt signaling pathway in glioma cells." (PMID 25394492, 2014). "Furthermore, YAP1 positively correlated with IGF1R gene expression in GBM in both the TCGA and Chinese Glioma Genome Atlas (CGGA) datasets." (PMID 41510300, 2025).
glioma (continued). "Recent research shows that nuclear localization of IGF1R leads to higher cell proliferation rates and earlier tumor development in pediatric gliomas, while cells become sensitive to OSI906 treatment, providing a new therapeutic direction for patients with gliomas with nuclear IGF1R localization." (PMID 39404930, 2024). "Nevertheless, the prognostic and therapeutic significance of IGF-1R-related signaling pathway genes (IGFIRS) in gliomas has not been investigated." (PMID 38665430, 2024). "The IGF-1/IGF-1R signaling can activate the PI3K/AKT/mTOR pathway signaling pathway, which is closely related to AKT1 and PIK3CD and plays a critical role in glioma progression, promoting cancer cell proliferation and inducing drug resistance." (PMID 38665430, 2024). "IGF-1R: IGF-1R receptor on activation promotes glioma cell proliferation and migration and may also trigger low-grade gliomas to progress to GBM." (PMID 36678688, 2022). "As a summary, we presented evidence that IGF1R nuclear localization stimulates cell motility and metabolism without affecting the cell proliferation of cultured glioma cells." (PMID 35574033, 2022). "Survival was significantly longer in patients with gliomas having non-nuclear IGF1R localization than in patients with nuclear IGF1R." (PMID 36479090, 2022). "Accordingly, in a previous study, we have described an increment in Cyclin D1 expression in pediatric gliomas where IGF1R had nuclear compared to non-nuclear localization." (PMID 35574033, 2022). "In glioma, lncRNA NCK1-AS1 upregulated radioresistance via miR-22-3p/IGF1R axis." (PMID 35600868, 2022). "IGF1R staining was mostly non-nuclear in low-grade tumors, while nuclear expression was predominant in high-grade gliomas." (PMID 33918477, 2021). "Survival was significantly longer in patients with gliomas having non-nuclear IGF1R localization than in patients with nuclear IGF1R tumors." (PMID 33918477, 2021). "It should be noted that, given that high concentration of insulin can also activate IGF1R, the minimal media used for nonadherent growth assay were devoid of insulin, which was otherwise routinely added for glioma cell culture in many studies." (PMID 33173731, 2020). "This concentration is far less than prior work which used 10–20 mg/kg in mice to exert brain effects on central control of body temperature or glioma growth and produced no lasting effects on brain p-IGF-1R levels." (PMID 32719587, 2020). "Therefore, we tested the effect of IGF2 on the phosphorylation of IGF-1R and AKT in TMZ-sensitive and TMZ-resistant glioma cells." (PMID 30231881, 2018). "Using chemoresistant and chemosensitive wild-type and transgenic glioma cells, we further found that a paracrine mechanism driven by IGFBP6 secreted from TMZ-sensitive cells abrogates the proliferation of IGF-1R-expressing TMZ-resistant cells in vitro and in vivo." (PMID 30231881, 2018). "Employing this strategy, they developed an antisense ODN (oligodeoxynucleotide) against the IGF-1R and in a Phase 0 human clinical trial demonstrated that ex-vivo IGF-1R antisense ODN treatment with patient derived autologous glioma cells safely induced apoptosis and a host response." (PMID 29113409, 2017). "It has been reported that glioma growth, invasion, and angiogenesis signals are related to ECM components such as collagen, laminin, and integrin, and to receptor tyrosine kinase (RTK) genes such as EGFR, PDGFR, IGF1R, and Met." (PMID 29161257, 2017). "In 1996, Resnicoff and co-workers demonstrated that C6 glioma cells expressing an antisense IGF-1R RNA were no longer tumorigenic in syngeneic rats, protected them from subsequent tumor re-challenge, and caused regression of established subcutaneous tumors." (PMID 29113409, 2017).
glioma (continued). "Using gene expression public databases, we confirmed that IGFBP2 is a poor prognosis marker for gliomas, and we also observed an important contribution of ADAMTS1.Finally, we showed the impact of ADAMTS1 on IGFII-mediated IGF1R phosphorylation and cellular migration." (PMID 24962328, 2014). "IGF-1R exerts its effect primarily through activating MAPK kinases and the PI3K/AKT pathways, that may further influence the invasion of glioma cells." (PMID 24378652, 2014). "BMS‐536924, an ATP‐competitive IGF‐1R/IR inhibitor, may significantly lower the survival rate of glioma cells regardless of TMZ resistance." (PMID 41438616, 2025). "The increased level of miR‐497 in TMZ‐resistant glioma cells was concurrent with the up‐regulation of insulin‐like growth factor 1 receptor (IGF1R)/insulin receptor substrate 1 (IRS1) pathway‐related proteins, that is, IGF1R, IRS1, mammalian target of rapamycin (mTOR), and Bcl‐2." (PMID 28064447, 2017). "It would be highly interesting to investigate whether those with glial tumors where the cells having OPC identities constitute the majority of the tumor mass, such as proneural subtype of GBM, oligodendrogliomas, and DIPGs, would particularly benefit from IGF1R targeted therapy." (PMID 33173731, 2020). "Chronic activation of olfactory receptor neurons in the olfactory bulb after knocking out IGF1R did not promote glioma growth, indicating that olfaction regulates glioma development through the IGF1‐IGF1R signaling pathway." (PMID 39469896, 2024). "It turned out that dual insulin-like growth factor 1 receptor/insulin receptor (IGF1R/IR) kinase inhibitors, BMS-754807 (BMS) and linsitinib (LIN), effectively inhibited the proliferation of glioma cells without negatively affecting CAR-T cells." (PMID 38339374, 2024). "Furthermore, we also found that, although MADM‐Mutant model fully developed glioma around 8 months, the MADM‐Mutant‐IGF1R model exhibited no obvious symptoms up to 400 days." (PMID 33173731, 2020). "In addition, the negative feedback modulating effect of SOCS1 on IGF-1R mediated signaling has been reported and whether SOCS1 can negatively inhibit IGF-1R signaling in gliomas is worthy of further study." (PMID 38665430, 2024).
gastric cancer (96 papers, 2010 to 2025). A primary or metastatic malignant neoplasm involving the stomach. "For instance, bufothionine induces gastric cancer cell apoptosis via up-regulating miR-133a-3p which sponges IGF1R and regulates PI3K/Akt associated production of reactive oxygen species." (PMID 33768092, 2021). "In breast and stomach cancers, the increased expression of IGF1R, GPC3, and IGFBP5 genes is associated with tumor progression and metastasis." (PMID 30944407, 2019). "We and others have shown that upregulation of IGF-1R in human tumor tissues is associated with higher tumor grade and poor survival in gastric cancer, cervical cancer, and NPC." (PMID 31467485, 2019). "IGF1R gene expression was associated with poor outcomes after curative resection of stage II/III gastric cancer, whereas AREG gene expression was associated with good outcomes." (PMID 26884344, 2017). "Many cancers express IGF‐1R and 75.2% of stomach cancer tissue expresses IGF‐1R, which may be the cause of poor prognosis." (PMID 30247804, 2018). "In patients with gastric cancer, elevated IGF1R levels were associated with lymph node metastasis." (PMID 28880250, 2017). "Finally, some glucose‐lowering therapies, such as sulfonylureas and insulin therapy, may increase gastric cancer risk by interacting with insulin and insulin IGF‐1R signaling." (PMID 38751364, 2024). "Multiple lines of evidence suggest that the upregulation of insulin-like growth factor 1 receptor (IGF1R) plays a crucial role in promoting carcinogenesis and drug resistance in gastric cancer." (PMID 40630212, 2025). "In gastric cancer, miR-7 directly inhibits the expression of IGF1R, EGFR, and mTOR, which are the downstream effectors of the PI3K/Akt pathway." (PMID 38200584, 2024). "In gastric cancer, miR-99b-5p suppressed proliferation via negatively modulating insulin-like growth factor 1 receptor (IGF-1R) and stimulating AKT pathway." (PMID 38632250, 2024). "A previous report demonstrated that TRAIL induces IGF1R activation in gastric cancer models, leading to resistance to TRAIL-induced cell death." (PMID 38200153, 2024). "In this study, we found that IGF1/IGF1R signaling is highly activated in GC, and inhibition of IGF1R potently suppresses the proliferation of gastric cancer cells." (PMID 36774408, 2023). "This interaction between IGF1R and miR-99a has been identified in several previous publications, such as cervical cancer, gastric cancer, and esophageal squamous cell carcinoma." (PMID 37582734, 2023). "Previous study has also demonstrated that IGF1R (encoding insulin-like growth factor 1 receptor, IGF-1R), an upstream gene of AKT/mTOR signaling, is a direct target of miR-99b-5p in gastric cancer." (PMID 36077039, 2022). "Previous studies have demonstrated that lncRNA NR2F1-AS1 can influence breast and gastric cancer progression by activating insulin-like growth factor-1 (IGF-1)/IGF-1R/ERK, MAP3K2, and AKT3, which crosstalk with AKT." (PMID 35283481, 2022). "miR-99b was previously reported to be a tumor suppressor by targeting IGF-1R in gastric cancer, while in this study, miR-99b is highly expressed in cancer patients and is supposed to be a tumor promoter." (PMID 34603485, 2021). "A variety of miRNAs, such as miR-1271, miR-143 and miR-503, have been observed to be involved in the IGF1R/IRS1 pathway-mediated DDP resistance of gastric cancer." (PMID 32192494, 2020). "The elevated expression of IGF1R was observed in tumor necrosis factor-related apoptosis-inducing ligand (TRAIL)-resistant gastric cancer cells, thus enhancing TRAIL resistance in gastric cancer cells." (PMID 32694937, 2020). "More importantly, MP subtype gastric cancer cells were more sensitive to inhibition of IGF1/IGF1R pathway." (PMID 29725014, 2018). "miR-7 also targets IGF-1R in a gastric cancer model with significant influence on inhibiting the metastatic potential in this model." (PMID 29973528, 2018).
gastric cancer (continued). "MiR-143, miR-503 and miR-1271 modulated cisplatin resistance of human gastric cancer cells by targeting IGF1R." (PMID 29642855, 2018). "Since analysis of genomic data from multiple cohorts suggested activation of the IGF1 pathway in MP subtype, we assessed activation status of the IGF1 receptor (IGF1R) in gastric cancer tissues with western blot experiments." (PMID 29725014, 2018). "In this study, the frequency of IGF1R amplification in Type IV was 3.8%, which was similar to that observed in the gastric cancer TCGA study." (PMID 27891760, 2017). "In conclusion, the current study provided compelling evidence that high IGF1R and low AREG expression were associated with poor prognosis after curative resection of stage II/III gastric cancer." (PMID 26884344, 2017). "miR-503 regulates cisplatin resistance of human gastric cancer cell lines by targeting IGF1R and BCL2." (PMID 32309578, 2016). "miR-1271 regulates cisplatin resistance of human gastric cancer cell lines by targeting IGF1R, IRS1, mTOR, and BCL2." (PMID 32309578, 2016). "Amplification of seven oncogenes: HER2, EGFR, FGFR1, FGFR2, MET, KRAS and IGF1R has been identified in gastric cancer." (PMID 27437872, 2016). "Our previously studies found that Klotho protein inhibited the activation of IRS-1 / PI3K / Akt / mTOR and ERK / p70s6k and downstream signaling pathways in gastric cancer and liver cancer cells, mainly through the inhibition of IGF-1R phosphorylation." (PMID 27779100, 2016). "Currently, the possibility that PI3K inhibitor and/or IGF-1R antibody in combination with auraptene can exhibit enhanced (synergistic) effects on the growth of human gastric cancer cells is under investigation in our laboratory." (PMID 26351512, 2015). "A recent report showed that miR-7 suppresses Snail, increases E-cadherin expression, and partially reverses EMT by targeting IGF1R, generating a novel miR-7/IGF1R/Snail axis in gastric cancer." (PMID 24598126, 2014). "It has been shown that overexpression of miR-7 inhibited tumor invasion and metastasis by targeting insulin-like growth factor-1 receptor (IGF-1R) in gastric cancer." (PMID 24816687, 2014). "The overexpression of miR-7 has been shown to partially reverse EMT to MET in gastric cancer by targeting the insulin-like growth factor-1 receptor (IGF1R)." (PMID 24944699, 2014). "Klotho is a tumor suppressor in gastric cancer, which regulates IGF-1R phosphorylation and the subsequent activation of IRS-1/PI3K/Akt/mTOR signaling, tumor cell proliferation, apoptosis, and autophagy." (PMID 23432957, 2013). "In this study, we revealed the prognostic value and biological functions of miR-598-3p and its targets RMP and IGF1r in gastric cancer, which explained why and how hypoxic gastric cancer cells acquire a metastatic tendency toward glucose metabolic reprogramming." (PMID 38491378, 2024). "Notably, BMS-754807, a selective IGF-1R inhibitor, exhibited potent inhibitory effects on gastric cancer cells." (PMID 38962317, 2024). "It has therefore been concluded that the miR-99a/IGF1R axis may provide novel insight into the pathogenesis of gastric cancer." (PMID 34315491, 2021). "Previous study has proven that the epithelial-mesenchymal transition (EMT) process of gastric cancer cells could be induced by IGF-1 through the IGF-1R/STAT3 signaling pathway so that cancer cells would achieve metastasis." (PMID 34804946, 2021). "IGF1R overexpression has been reported in patients with gastric cancer." (PMID 32577155, 2020). "Furthermore, STAT3 signaling was reported to be involved in IGF1/IGF1R‐mediated cell growth and metastasis in gastric cancer." (PMID 32851683, 2020). "For instance, miR-99b expression was demonstrated to be reduced in gastric cancer tissues and cell lines, and it could suppress the tumor cell proliferation and cell cycle by targeting IGF-1R." (PMID 31651329, 2019).